HSD17B13 (hydroxysteroid 17-beta dehydrogenase 13)
Diseases named in the same sentence as HSD17B13 in open-access papers (continued):
Sharing a sentence is not in itself a finding about the gene and the disease.
Hepatic steatosis (24 papers, 2020 to 2026). Steatosis is a term used to denote lipid accumulation within hepatocytes. "While adenovirus-mediated overexpression of human HSD17B13 in mice has been linked to elevated hepatic lipid levels, its genetic deletion has also been associated with exacerbated liver steatosis or macro-vesicular steatosis." (PMID 39496977, 2024). "Single‐nucleotide polymorphisms (SNPs) in PNPLA3 and hydroxysteroid 17‐beta dehydrogenase 13 (HSD17B13) genes are associated with fatty liver disease (FLD) progression and carcinogenesis." (PMID 37644826, 2023). "The HSD17B13 genetic variant rs72613567 minor allele also reduced liver damage and even hepatic steatosis among obese children." (PMID 34208839, 2021). "Moreover, it is interesting to note that HSD17B13 has also an anti-inflammatory role, since its deficiency triggers hepatic steatosis and inflammation in mice." (PMID 36941576, 2023). "However, the correlation between simple hepatic steatosis and the HSD17B13 genetic variant was refuted by some clinical data." (PMID 34208839, 2021). "Similarly, another group reported that mice deficient of the HSD17B13 gene spontaneously developed late-onset fatty liver at the age of 9 months under normal chow." (PMID 35071330, 2021). "However, HSD17B13 deficiency also resulted in liver steatosis." (PMID 35628360, 2022). "We speculate that this extra-hepatic effect of the HSD17B13 S33A mutation is secondary to hepatic insulin resistance caused by liver steatosis, which reflects a critical role of HSD17B13 in hepatocytes, consistent with the highly selective expression of HSD17B13 in the liver." (PMID 36323699, 2022). "In addition, it has also been reported that HSD17B13 may mediate LXRα activation-associated liver steatosis via a SREBP1-dependent mechanism." (PMID 35071330, 2021). "Our RNAi therapeutic approach, to suppress Hsd17b13 levels in adult mice with existing HFD‐induced liver steatosis to decrease hepatic triglyceride storage is a translational approach to investigate the role of Hsd17b13 in MASLD." (PMID 40016916, 2025). "In mice, hepatic overexpression of human HSD17B13 increases liver TAG and cholesterol levels, while abrogation of the mouse Hsd17b13 gene was reported to both promote hepatic steatosis and inflammation or to have limited effects on MASH." (PMID 39395791, 2024). "It was found that a variety of gene sites are related to the risk, disease severity, hepatic steatosis and advanced fibrosis of NAFLD, including PNPLA3, TM6SF2, GCKR, MBOAT7, APOC3, HSD17B13, etc.." (PMID 36973654, 2023). "When HSD17B13 was overexpressed in the liver, it aggravated liver steatosis and fibrosis in mice fed with a high-fat diet, while down-regulated the high expression of HSD17B13 by short hairpin RNAs produced a therapeutic effect in the NAFLD mice." (PMID 35628360, 2022). "High HSD17B13 expression led to liver steatosis in C57BL/6 mice, and subsequent studies demonstrated that liver X receptor alpha activation induced high HDS17B13 expression and thus led to the development of fatty liver disease." (PMID 35628360, 2022). "In addition, HSD17B13 stabilized intracellular TGs and thus might cause unbalance of LDs in the liver, which might hinder autophagy and lipolysis processes, and sequentially worsen liver steatosis to NASH." (PMID 35628360, 2022). "Genetic variations (PNPLA3, TM6SF2, GCKR, MBOAT7, MERTK, and HSD17B13) are one of the non-modifiable risk factors for metabolic dysfunction-associated fatty liver disease (MAFLD) and MASLD." (PMID 40507973, 2025). "The other European cohort performing a GWAS did not detect a correlation between the HSD17B13 genetic variant and hepatic steatosis." (PMID 34208839, 2021).
Hepatic steatosis (continued). "Furthermore, understanding interspecies differences may be key to unraveling the mechanism of action of human HSD17B13 and advancing its role as a therapeutic target for fatty liver." (PMID 38344397, 2024). "The factors included age, gender, BMI, T2DM, HT, DLP, AST, ALT, platelet count, liver steatosis grade, PNPLA3 rs738409, TM6SF2 rs58542926, and HSD17B13 rs6834314; as well as VCTE, M2BPGi, FIB-4, APRI, and NFS." (PMID 40002828, 2025). "Genetic variants in “glucokinase regulatory protein” (GCKR) gene, “solute carrier family 2-member 1” (SLC2A1) gene, and “17-beta hydroxysteroid dehydrogenase 13” (HSD17B13) gene, have also been identified in patients with fatty liver disease." (PMID 36976456, 2023). "Our findings demonstrate, for the first time, that Hsd17b13 ASO effectively suppressed Hsd17b13 gene expression both in vitro and in vivo, and had a modulatory effect on hepatic steatosis in mice, but did not affect fibrosis in the CDAHFD mouse model of NASH." (PMID 38309418, 2024). "Studies of HSD17B13 LOF and siRNA silencing of HSD17B13 mRNA found that hepatic steatosis was unaffected in subjects, and it was tentatively concluded that the lack of preventive effect of HSD17B13 on NASH and other related diseases is unlikely to be due to reduced metabolism of hepatic fat stores." (PMID 38344397, 2024). "However, the traditional gene knockout of Hsd17b13 in mice had no beneficial effect on the development of liver steatosis with various dietary interventions." (PMID 40016916, 2025). "For instance, five variants in or near TM6SF2, PNPLA3, HFE, APOE, and MTARC1 had comparably larger effects on HCC than on hepatic steatosis (p <0.05 by Cochran’s Q test), while HCC-associated variants in HSD17B13, KLF15, and TERT did not significantly associate with steatosis." (PMID 40823170, 2025). "In L02 cells incubated with a high concentration of OA, HSD17B13 increased the contents of LDs, while the other transcripts did not increase, suggesting that HSD17B13, the full-length protein, might be the main causative factor for the early occurrence of NAFLD, especially the liver steatosis." (PMID 35628360, 2022).
liver fibrosis (22 papers, 2020 to 2026). "The protection against liver fibrosis conferred by the hydroxysteroid, 17-beta dehydrogenase 13 (HSD17B13), is associated with reduced dihydropyrimidine dehydrogenase-mediated pyrimidine catabolism." (PMID 39917615, 2025). "For example, a recent study in Japan demonstrated that the HSD17B13 rs6834314 AG/GG variants were associated with increased steatosis grading but exhibited an attenuated effect of PNPLA3 on advanced hepatic fibrosis." (PMID 39596570, 2024). "We recently reported that carriage of the HSD17B13 rs6834314 G allele attenuated the effect of the PNPLA3 rs738409 GG genotype on advanced hepatic fibrosis." (PMID 33922278, 2021). "Carriers of rs7261357:TA, a gene variant of Hydroxysteroid 17‐Beta Dehydrogenase 13 (HSD17B13), have been shown to correlate with decreased hepatic fibrosis and downregulation of the expression of inflammatory gene expression." (PMID 40833357, 2026). "PRS-5 based on variations in PNPLA3, TM6SF2, GCKR, MBOAT7, and HSD17B13 is also useful for the prediction of liver fibrosis." (PMID 40507973, 2025). "Only after adjusting for the risk factors (age, sex, BMI, WC, HDL, TG, diabetes mellitus, and hypertension) F2 liver fibrosis score is negatively correlated with the HSD17B13 rs9992651 GA genotype." (PMID 38674389, 2024). "The results of this study suggest that carriage of HSD17B13 rs6834314 AA showed resistance to the therapeutic effects of BW reduction in the improvement of liver fibrosis." (PMID 33922278, 2021). "Recently, the genetic variant (rs72613567:TA) in hydroxysteroid 17-beta dehydrogenase 13 (HSD17B13) was shown to be associated with decreased risk of NASH and liver fibrosis." (PMID 32051820, 2020). "This is the first study to investigate the relationship between the PNPLA3 rs738409, TM6SF2 rs58542926, GCKR rs1260326 and rs780094, MBOAT7 rs641738, HSD17B13 rs72613567, and MTARC1 rs2642438 polymorphisms in the Brazilian population with MASLD and liver fibrosis." (PMID 40650184, 2025). "Due to the proven role of the rs72613567 insertion/deletion variant of HSD17B13, it could serve as a potential target for genetic-based precision medicine to treat NASH and liver fibrosis." (PMID 38504356, 2024). "However, the overactivation of these healing processes leads to the onset of progressive liver fibrosis, especially in individuals with increased susceptibility to liver fibrosis due to gene polymorphisms, such as PNPLA3, TM6SF2, and HSD17B13." (PMID 35563210, 2022). "Studies have shown that HSD17B13 may regulate the HSCs activity and participate in the development of liver fibrosis." (PMID 36225559, 2022). "In addition, this is the first study to investigates the relationship between the rs738409 (PNPLA3), rs58542926 (TM6SF2), rs1260326 and rs780094 (GCKR), rs641738 (MBOAT7), rs72613567 (HSD17B13), and rs2642438 (MTARC1) polymorphisms in the Brazilian population with MASLD and hepatic fibrosis." (PMID 40650184, 2025). "Likewise, INI-678 (an HSD17B13 inhibitor), introduced by Inipharm, has demonstrated efficacy in decreasing liver fibrosis in a human liver-on-a-chip-model, opening a gate for broader application of small-molecule therapy in genetic-based precision medicine of NAFLD." (PMID 38504356, 2024). "In conclusion, Hsd17b13 knockdown in HFD‐obese adult mice was able to alleviate MASLD via regulation of fatty acid and phospholipid metabolism, thereby confirming HSD17B13 as a genuine therapeutic target for MASLD and the development of liver fibrosis." (PMID 40016916, 2025). "HSD17B13 seems to be one of the therapeutic targets for MASLD and the development of liver fibrosis." (PMID 40507973, 2025). "As we mentioned, the PNPLA3 and HSD17B13 genotypes are in a mutual relationship in pathology of NAFLD, and improvement of liver fibrosis is more important than that of steatosis." (PMID 33922278, 2021).
liver fibrosis (continued). "In vivo experiments using two different liver fibrosis mouse models showed a weakening effect on liver fibrosis, and we reported that along with YAP-CTGF, HSD17B13, which is involved in retinoic acid metabolism and nonalcoholic fatty liver disease, was associated with this effect." (PMID 37765160, 2023). "Subsequent findings indicate that the suppression of pyrimidine catabolism in mice lacking HSD17B13 may underpin the impact of HSD17B13 on the progression of liver fibrosis." (PMID 39496977, 2024).
hepatocellular carcinoma (21 papers, 2017 to 2025). A malignant tumor that arises from hepatocytes. "Five literatures described the association between HSD17B13 rs72613567: TA allelic variant and susceptibility to hepatocellular carcinoma (HCC) compared with chronic liver disease (NAFLD, ALD, viral hepatitis)." (PMID 34930143, 2021). "The present findings suggest HSD17B13 rs72613567:TA allelic variant can reduce the risk of hepatocellular carcinoma and NAFLD in the entire population studied." (PMID 34930143, 2021). "The occurrence of single nucleotide variants rs738409 in the PNPLA gene and rs58542926 in transmembrane 6 superfamily member 2 gene (TM6SF2) associate with the risk of hepatocellular carcinoma, whereas variant rs4607179 of hydroxysteroid 17-beta dehydrogenase gene (HSD17B13) reduces the risk." (PMID 34298760, 2021). "Besides, we not only analysis the association between HSD17B13 rs72613567: TA allelic variant and susceptibility to hepatocellular carcinoma (HCC) compared with healthy controls, but also compared with CLD." (PMID 34930143, 2021). "Importantly, the risk of hepatocellular carcinoma was also decreased in patients heterozygous (OR = 0.65) and homozygous (OR = 0.28) for the HSD17B13 rs72613567:TA allele." (PMID 35071330, 2021). "The HSD17B13 gene variant rs72613567 (T > TA) confers protection against MASLD, alcoholic liver disease, and hepatocellular carcinoma by reducing hepatic lipid biogenesis." (PMID 40004240, 2025). "HSD17B13 is involved in estrogen biosynthesis, and its tumor suppressor role in hepatocellular carcinoma has been documented, suggesting analogous key roles specific to breast cancer progression." (PMID 37287543, 2023). "Patients with the HSD17B13 A/A genotype showed increased incidence of hepatocellular carcinoma, cardiovascular diseases, and hypertension." (PMID 37644826, 2023). "HSD17B13 expression has also been shown to inhibit the progression and recurrence of hepatocellular carcinomas." (PMID 34884649, 2021). "Recently, there have been several reports that predicted loss of function variants in HSD17B13 protect against the progression of steatosis to non-alcoholic steatohepatitis with fibrosis and hepatocellular carcinoma." (PMID 37620305, 2023). "In addition, overexpressing HSD17B13 in the Huh-7 and SK-HEP-1 hepatoma cell lines led to an increase of cells in the G1 phase of the cell cycle, suggesting that HSD17B13 could potentially delay the cell cycle." (PMID 34208839, 2021). "HSD17B13 suppresses the Warburg effect, reducing hepatocellular carcinoma (HCC) tumor growth." (PMID 40426878, 2025). "Compared to patients with HSD17B13 A/A and others, those with the A/A genotype showed increased incidence of hepatocellular carcinoma (HCC) (A/A vs. others; 18.4% vs. 9.5%, p = 0.01), cardiovascular diseases (14.2% vs. 4.2%, p < 0.01), and hypertension (56.6% vs. 47.4%, p = 0.06)." (PMID 37644826, 2023). "Neither overexpression nor knockdown of HSD17B13 in HepG2 (human hepatoma cells) was shown to impact lipid storage." (PMID 39395791, 2024). "HSD17B13 does not have a known function, but was suggested as a biomarker for hepatocellular carcinomas." (PMID 29228658, 2017).
non-alcoholic fatty liver disease (19 papers, 2019 to 2025). "Various isoforms of 17-β-hydroxysteroid dehydrogenase, namely HSD17B13, have previously been found to be associated with non-alcoholic fatty liver disease and HCC recurrence and progression." (PMID 40040391, 2025). "A LoF variant (rs72613567) in HSD17B13 has been linked to a reduced risk of chronic liver and non-alcoholic fatty liver disease." (PMID 39488654, 2024). "HSD17B13, on the other hand, is involved in steroid hormone metabolism, and mutations in this gene are associated with non-alcoholic fatty liver disease and insulin resistance." (PMID 37240140, 2023). "Hydroxysteroid 17-beta-dehydrogenase 13 (HSD17B13) is a hepatic lipid droplet-associated enzyme that is upregulated in patients with non-alcoholic fatty liver disease." (PMID 37620305, 2023). "Contrariwise, although the variant in HSD17B13 was linked with decreased levels of the spliced variant, it has been associated with protection against alcoholic and non-alcoholic fatty liver disease and against the progression towards fibrosis and HCC." (PMID 36233142, 2022). "A common loss-of-function variant of HSD17B13 (rs72613567: TA) protects patients against non-alcoholic fatty liver disease with underlying mechanism incompletely understood." (PMID 36323699, 2022). "In 2018, a genetic variant (rs72613567, T > TA) of hydroxysteroid 17-β dehydrogenase family 13 (HSD17B13) was first associated with a lower risk of developing alcoholic liver disease and non-alcoholic fatty liver disease (NAFLD) in minor allele carriers." (PMID 34208839, 2021). "More recently, the enzyme 17-beta hydroxysteroid dehydrogenase 13 (HSD17b13) with retinol dehydrogenase activity, was implicated in the pathogenesis of non-alcoholic fatty liver disease." (PMID 31717719, 2019). "Recently, one of those members, 17β-HSD13 (HSD17B13), has garnered significant interest after a potential role in the pathogenesis of non-alcoholic fatty liver disease (NAFLD) was identified through genome-wide association studies." (PMID 37620305, 2023). "Additionally, hydroxysteroid (17- beta) dehydrogenase 13 (Hsd17b13) is a key member of the 17β-hydroxysteroid dehydrogenase (HSD17B) family and is highly expressed in nonalcoholic fatty liver disease." (PMID 38532405, 2024).
steatosis (18 papers, 2020 to 2025). Increased lipid within the cytoplasm of cells. "Hispanic ethnicity and genetic polymorphisms in PNPLA3, TM6SF2, GCKR, MBOAT7, and HSD17B13 are associated with steatosis-related lipotoxicity and oxidative DNA damage, which can contribute to hepatocarcinogenesis." (PMID 40995256, 2025). "Regarding steatosis, our data showed that HSD17B13 rs6834314 GA + GG was an independent factor associated with moderate/severe steatosis assessed by MRI-PDFF." (PMID 39596570, 2024). "In NAFLD subjects, the minor allele rs6834314 of HSD17B13 was associated with increased steatosis, but decreased inflammation and ballooning via its hepatic retinol dehydrogenase activity." (PMID 33922278, 2021). "Another GWAS study identified that rs6834314 A > G variant near the HSD17B13 gene is associated with increased steatosis and NAFLD histology." (PMID 34503201, 2021). "However, the role of the HSD17B13 variant in association with increased steatosis is inconsistent among reports." (PMID 39596570, 2024). "Moreover, the HSD17B13 variant was significantly associated with the degree of steatosis." (PMID 39596570, 2024). "Recent data also suggest that a loss-of-function variant in the 17-beta hydroxysteroid dehydrogenase 13 gene (HSD17B13) is associated with a reduced risk of chronic liver disease and of progression from steatosis to steatohepatitis and, thus, may represent another factor in HCC development." (PMID 38672997, 2024). "For instance, a recent Japanese study revealed that the HSD17B13 rs6834314 AG + GG genotypes were related to enhanced steatosis but displayed a reduced effect of PNPLA3 on advanced fibrosis." (PMID 40725464, 2025). "Background/Objectives: This study evaluated the association between polymorphisms in the PNPLA3, TM6SF2, HSD17B13, and SIRT5 genes and the severity of fibrosis and steatosis in metabolic dysfunction-associated steatotic liver disease (MASLD)." (PMID 39596570, 2024). "Loss of the function variant of HSD17B13 (rs72613567, an insertion of an adenine) is associated with reduced levels of alanine aminotransferase (ALT) and aspartate aminotransferase (AST) as well as of progression from steatosis to steatohepatitis." (PMID 34503201, 2021). "Conversely, genetic variants in Hydroxysteroid 17-β Dehydrogenase 13 (HSD17B13) are protective against disease progression to advanced fibrosis but might not prevent the development of steatosis." (PMID 39596570, 2024). "Recent findings also suggest that a loss-of-function variant in the hydroxysteroid 17 beta dehydrogenase 13 (HSD17B13) gene may reduce the risk of chronic liver disease and the progression from steatosis to steatohepatitis, potentially affecting HCC development." (PMID 39000296, 2024). "In terms of the effect of HSD17B13 on liver pathology, the rs72613567:TA variant is associated with a reduced risk of NASH but not steatosis." (PMID 37644826, 2023). "Patients without HSD17B13 A/A showed severe steatosis (77% vs. 88.6%, p < 0.01)." (PMID 37644826, 2023).
fibrosis (6 papers, 2021 to 2024). the formation of excess fibrous connective tissue in an organ or tissue in a reparative or reactive process. "Despite the well documented variation in the prevalence of higher genotypes conveying greater risk of more advanced fibrosis with ethnicity e.g., for HSD17B13 and PNPLA3, ethnicity was not predictive of stage of fibrosis in this analysis." (PMID 37208593, 2023).
non-alcoholic steatohepatitis (6 papers, 2020 to 2026). "Additionally, GSK4532990 has been identified as a potential drug targeting HSD17B13 for the treatment of non-alcoholic steatohepatitis." (PMID 39092217, 2024). "A drug targeting HSD17B13, INI-822, has been found to be applicable for fibrotic liver diseases, including non-alcoholic steatohepatitis, and is currently undergoing Phase I clinical trials." (PMID 39092217, 2024).